FGFR2 (fibroblast growth factor receptor 2)
Diseases named in the same sentence as FGFR2 in open-access papers (continued):
Sharing a sentence is not in itself a finding about the gene and the disease.
tumor (continued). "As Fgfr2 activation enhances Brca1‐deficient tumor formation, we explored whether Fgfr2 inhibition is a viable therapeutic option for Brca1‐associated tumors." (PMID 34514747, 2021). "We previously reported that splicing variant of FGFR2 IIIb type and FGFR2 IIIc type might be regulated the oxidative level of tumor microenvironment." (PMID 33633310, 2021). "Notably, loss of expression of both FGFR2 isoforms (FGFR2b-/FGFR2c-) was found in 13 tumour samples (4 of these were excluded from outcome analyses) with loss of both FGFR2 isoforms also associated with progestin treatment failure." (PMID 33916719, 2021). "Different investigations have proven that amplifications of the FGFR2 (occurring in less than 5% of triple negative breast cancers), and other mutations activating the FGFRs have been related with maintenance of tumor-initiating cells and a high sensitivity to FGFR inhibitors." (PMID 32188012, 2020). "With regard to the prognostic factors, the FGFR2 SNP rs1219648 was associated with tumor differentiation (p-value = 0.018), the MAP3K1 SNP rs889312 was linked to the HER2 marker (p-value = 0.04), and the IGF1 SNP rs2373721 was correlated with progesterone receptor status (p-value = 0.04)." (PMID 33112566, 2020). "In addition, FGFR-2 expression is associated with decreased tumor progression in some tumors, such as astrocytomas, bladder, prostate, and thyroid carcinomas." (PMID 32012988, 2020). "Several downregulated genes were shown to have a strong protein interaction, but most of these genes, such as Fgfr2, Tnc, and Lef1, have been positively associated with tumor progression, suggesting their downregulation is not involved in 4C11+ cells aggressive phenotype." (PMID 31069961, 2019). "Furthermore, we identified a posttreatment secondary kinase mutation in FGFR2 present in a single metastatic tumor sample and characterized its impact on sensitivity to a variety of FGFR inhibitors in vitro." (PMID 31371345, 2019). "FGFR2 mutations were only observed in eight cell lines, distributed over seven tumor types." (PMID 28903445, 2017). "We hypothesized that FGFR2 amplification is associated with FGFR2 expression, resulting in tumor growth and poorer outcome in esophagogastric junction (EGJ) adenocarcinoma." (PMID 26933914, 2016). "In addition, patients with tumours positive for either or both FGFR2 and RSK-P had 4.89-fold higher risk of recurrence when compared to the FGFR2/RSK-P-negative subgroup." (PMID 27476168, 2016). "Evidence that genetic variants in FGFR2 may influence tumor subtype is provided by the fact that susceptibility loci in FGFR2 have stronger associations for estrogen receptor positive disease (ER+) than ER−." (PMID 26421298, 2015). "We sequenced the protein-coding exons 5 and 7–9 in about 50 patients and exons 12–15 in about 140 patients as well as adjacent intronic sequences and we identified one novel heterozygous missense mutation in exon 14 of FGFR2, c.1980G>C, in tumor tissue of one of them (BC80)." (PMID 23527311, 2013). "Unfortunately, our sample set was too small to conclusively establish whether expression levels of FGFR2 mRNA in tumor-derived fibroblasts are similarly associated with SNP genotypes in intron 2 as they are in skin-derived fibroblasts." (PMID 21767389, 2011). "Interestingly, it is known that a mutation in FGFR2 expressed in these cells confers a selective advantage, thereby leading to clonal expansion similar to that seen in tumours." (PMID 16159394, 2005). "Importantly, a confirmed response was observed in a patient with an unknown primary tumor bearing the FGFR2 Y375C mutation." (PMID 37980453, 2023). "Therefore, we suggest that FGFR2 polymorphism may affect the FGFR2-mediated signaling pathway and promote tumor angiogenesis; if so, this may appear as an increased mean transit time on CEUS." (PMID 37120792, 2023).
tumor (continued). "Additionally, WES revealed an FGFR2 N549H mutation hypothesized to confer resistance to the FGFR inhibitor INCB054828 in a single tumor sample." (PMID 31371345, 2019). "Thus, present study investigated whether 5 common FGFR2 SNPs were associated with specific tumor subtypes defined by four markers." (PMID 26421298, 2015). "Finally, the clear differences observed for some SNPs (most notably for FGFR2 rs2981582, where the association was limited to ER-positive disease) suggest that the effect of misclassification in tumour subtype on the SNP associations is likely to have been small." (PMID 22053997, 2011). "Then we showed that dual blocking SHP2 and FGFR2 enhanced the effects of FGFR2 inhibitor (FGFR2i) in FGFR2-amplified GC both in vitro (human GC cell lines) and in vivo (mouse xenograft tumor models) via suppressing RAS/ERK and PI3K/AKT pathways." (PMID 41870032, 2026). "In xenograft models, 3H-3000 significantly inhibits tumor growth, underscoring its therapeutic promise for FGFR2-IIIb-driven tumors." (PMID 41584352, 2026). "A series of 99mTc-labeled peptides, particularly [99mTc]Tc-FGFR2-1, exhibited specific binding to FGFR2 with excellent tumor uptake and retention in DU145 xenograft models." (PMID 41584352, 2026). "In xenograft models, msFGFR2-IIIc significantly suppressed tumor growth, suggesting its utility in cancers co-expressing FGFR2-IIIc and FGFR1-IIIc isoforms." (PMID 41584352, 2026). "Downregulation of RBM4, driven by miR-92a, leads to increased nPTB expression and a shift toward FGFR2-IIIc, thereby promoting tumor progression via AKT/ERK activation." (PMID 41584352, 2026). "The patient's FGFR2-fused tumor responded favorably to lirafugratinib, allowing for delayed but successful resection following systemic therapy." (PMID 41148465, 2026). "The fibroblast growth factor receptor 2 (FGFR2) increases tumor cell proliferation and survival, and its overexpression is linked to aggressive tumors." (PMID 40724877, 2025). "Genetic and epigenetic modifications of FGFR2 result in its overexpression, fusion proteins, and enhanced ligand-binding affinity in tumor cells." (PMID 41430037, 2025). "This supports the idea that the subtype-specific immune environment provides the setting favourable for the crosstalk between FGFR2-mediated and ER pathways to promote tumour evolution." (PMID 41018083, 2025). "These subtype-specific interactions suggest a synergistic role of FGFR2 and estrogen receptor signalling in immune evasion and tumour progression, warranting further mechanistic and therapeutic investigation." (PMID 41018083, 2025). "By enhancing both HRR and NHEJ, FGFR2 alterations create functional redundancy that protects tumour cells from DNA-damaging agents." (PMID 41150770, 2025). "αSMA+ fibroblasts were close to tumor cells in both FGFR2+ and IDH1+ tumors, compared to other subtypes, highlighting their potential roles in mediating interactions among the included cell types." (PMID 39969434, 2025). "Treatment with derazantinib and GEM synergistically inhibited the malignant behaviors of GEM-resistant PDAC cells and tumor growth by downregulating FGFR2 and FGFR3 expression." (PMID 41467942, 2025). "A recent study revealed that FGFR2 signaling drives NF-κB–dependent glycolysis in iCCA, and that treatment with pemigatinib, infigratinib, or futibatinib can effectively reprogram tumor metabolism, thereby conferring a novel targetable vulnerability in iCCA." (PMID 40980689, 2025). "The FGFR2 gene is involved in the activation of the RAS–MAPK and PI3K–AKT pathways, and the NF2 tumour suppressor gene is typically mutated in most nervous system tumours." (PMID 41573648, 2025). "CD44 knockdown reduced FGFR2 expression and impaired tumor formation, and the reverse was also observed, as FGFR2 knockdown reduced CD44 levels and stem cell markers, paradoxically increasing c-Myc and SOX-2." (PMID 41303727, 2025).
tumor (continued). "FGFR2+ tumor cells were observed clustering near SFRP1+ cells, indicating a preferential association between the two." (PMID 40225580, 2025). "Characteristics of tumour-infiltrating immune cells, FGFR2 expression and ER and HER2 status in the study group." (PMID 41018083, 2025). "For example, tumours harbouring NTRK fusions now have targeted options such as Larotrectinib and Entrectinib, while tumours with FGFR2 fusions can be treated with Pemigatinib and Futibatinib, and tumours carrying IDH1 mutations can be treated with Ivosidenib." (PMID 40723185, 2025). "In particular, FGFR2 staining intensity on neoplastic cells differed between G1 and G2 tumor grades." (PMID 40806365, 2025). "Given the tumor’s proximity to critical structures and confirmed FGFR-2 fusion, systemic therapy with pemigatinib and sintilimab was initiated." (PMID 40255433, 2025). "The most abundant cell types within the tumor immune microenvironment in the FGFR2+ cohort were CD11b+/CD15+ granulocytes, followed by macrophages." (PMID 39969434, 2025). "Biopsy specimens should be the first medium to test for FGFR2 expression, with at least six samples recommended so as to minimize false negatives due to tumor heterogeneity." (PMID 41303727, 2025). "Alterations in fibroblast growth factor receptor 2 (FGFR2), although rare, are emerging as important contributors to tumor progression and drug resistance." (PMID 41150770, 2025). "These alterations were reversed in the shFGFR2 and Echinomycin groups, suggesting SFRP1 promotes tumor stemness and metastasis through FGFR2 and HIF1 pathway." (PMID 40225580, 2025). "Imatinib-resistant tumours that harbour FGFR2 fusions or amplifications maintain phosphorylation of ERK and AKT despite complete inhibition of KIT." (PMID 41150770, 2025). "Next, taking into account the possible association between the FGFR2-TIME crosstalk and BCa evolution, the relationship between expression of FGFR2 on tumour cells and markers of TIME’s features was analysed in all cases (N=99)." (PMID 41018083, 2025). "Compared with adjacent non-tumor tissues, FGFR2 expression was significantly up-regulated in 56 PDAC tissues." (PMID 41467942, 2025). "The current work shifts the focus to luminal BCa, where the biological context in ER+ tumours differs substantially, both in terms of baseline immunogenicity and the role of FGFR2 in BCa signalling network." (PMID 41018083, 2025). "Two papers distinguished between fusion and rearrangements finding that most of the tumours have FGFR2 fusions." (PMID 40205008, 2025). "Here, we show that the immune effects of FGFR2 are detectable at the earliest stages of tumour development and appear to be restricted to the ER+ subtype." (PMID 41018083, 2025). "This case highlights the efficacy of pemigatinib-based systemic therapy in achieving tumor regression and enabling curative resection in locally recurrent FGFR-2-positive ICC." (PMID 40255433, 2025). "FGFR2, in particular, has been shown to be overexpressed in CRC and is associated with tumor progression and poor prognosis." (PMID 40871637, 2025). "Circulating tumor DNA (ctDNA) is DNA fragments released by tumor cells, which can show tumor-specific gene mutations (such as IDH1/2, FGFR2 fusion) and epigenetic modifications (such as abnormal methylation)." (PMID 40673275, 2025). "Futibatinib is an irreversible FGFR1-4 inhibitor that was first described in 2020, demonstrating potent tumor growth inhibition in multiple preclinical cancer models with FGFR2 expression." (PMID 41303727, 2025).
tumor (continued). "Despite these advancements, the small prevalence of FGFR2 amplification and overexpression, tumor heterogeneity, and the emergence of resistance mechanisms represent challenges in the directed treatment of these tumors." (PMID 41303727, 2025). "I was offered the opportunity to enter a national genomic tumour testing program, and a FGFR2-fusion in my tumour was identified." (PMID 41237268, 2025). "NCCN and ESMO recommend, at minimum, testing for fusions in FGFR2 and NTRK, mutations in IDH1 and BRAF, over-expression or amplifications of HER2/ERBB2, tumor-mutational burden (TMB), and microsatellite instability (MSI)." (PMID 39996880, 2025). "Molecular analysis of the tumor via the TruSight-RNA-Fusion panel detected a fusion involving FN1::FGFR2, consistent with CCMN." (PMID 39404883, 2025). "FGFR2 expression was elevated in malignant epithelial cells, pointing to its potential role in tumor progression." (PMID 40225580, 2025). "FGFR3 was positive in the molecular layer of the cerebellar cortex and tumor cells, while FGFR2 was positive in tumor cells, glial cells, and blood vessels, and FGFR4 was positive in tumor cells, astrocytes, and blood vessels." (PMID 40393028, 2025). "Among patients exhibiting FGFR2 fusion, two showed stable tumor disease, and two demonstrated a partial tumor response." (PMID 38730642, 2024). "After adjusting for the age at diagnosis, nodal status, tumour stage at diagnosis, and survival outcome, the HER2-enriched molecular subtype was the only factor significantly associated with FGFR2 expression levels." (PMID 39596875, 2024). "The observed opposite trends in NOTCH1 and FGFR2 expression can be attributed to their distinct roles in tumor biology." (PMID 39063983, 2024). "Genomic analysis revealed the patient’s tumor was heterogenous—the highly FDG avid liver lesion harbored an FGFR2 translocation, whereas the hepatic lesion with low-level FDG avidity did not." (PMID 38714664, 2024). "Pre-clinical biodistribution studies confirmed the tumour-specific targeting of FGFR2-TTC, which also demonstrated promising pre-clinical efficacy in FGFR2-amplified xenograft models including SNU-16 GC cells." (PMID 38791079, 2024). "In preclinical studies, BAY 1187982 displayed efficient internalization and robust anti-tumour activity both in vitro and in vivo in FGFR2-amplified GC cell lines." (PMID 38791079, 2024). "In vivo studies demonstrated that the FGFR2 inhibitors ponatinib and infigratinib inhibited tumor growth and resensitized cells resistant to HER2-targeted therapies." (PMID 39123362, 2024). "Such successes are exemplified by BTC-specific approvals of fibroblast growth factor receptor (FGFR) inhibitors for tumours with FGFR2 rearrangements, as well as mutant isocitrate dehydrogenase 1 inhibitors." (PMID 41647592, 2024). "We identified three tumours with FGFR2 fusions, two of which had FGFR2 fusions in combination with BICC1." (PMID 38877653, 2024). "FGFR2 inhibitors, such as pemigatinib and futibatinib, inhibit tumor cell growth in FGFR‐driven cancers by receptor autophosphorylation and subsequent activation of FGF/ FGFR signaling." (PMID 38532197, 2024). "While NOTCH1’s tumor-suppressive functions are more prominent in the initial, less aggressive stages of tumor formation, FGFR2’s oncogenic activities drive tumor progression and malignancy." (PMID 39063983, 2024). "The peptides were each conjugated to doxorubicin to enhance their efficacies in targeting FGFR2 overexpressed tumor cells." (PMID 39329537, 2024). "Lirafugratinib is currently being clinically tested in a phase I/II tumour agnostic study of patients with FGFR2 alterations (ReFocus trial), comprising a dose escalation, dose expansion and extension phase (NCT04526106)." (PMID 38791079, 2024). "Here we present clinical histories and blood-based biomarker trends for the carbohydrate antigen 19-9 (CA19-9) tumor marker and FGFR2 fusion level measured by FGFR-Dx, a novel FGFR-focused sequencing assay." (PMID 39289482, 2024).
tumor (continued). "Possible reasons for suboptimal responses include co-occurring molecular drivers or tumor microenvironment unique to each cancer type, as well as the FGFR2 behavior dependent on its fusion partner." (PMID 39759134, 2024). "In another Phase II study, TAS-120 demonstrated comparable anti-tumor activity in patients with advanced or metastatic gastric and gastroesophageal cancer harboring FGFR2 amplification, with median PFS and OS estimates of 2.8 months and 5.7 months." (PMID 38831455, 2024). "The more aggressive HER2+ tumours had higher levels of exon 9 (indicative of the FGFR2 IIIc isoform), while TNBC had lower IIIb and IIIc expression levels compared to ER/PR-positive cancers." (PMID 39596875, 2024). "Nevertheless, several trials involving multi-kinase or pan-FGFR kinase inhibitors are currently ongoing in patients with FGFR2-altered tumours including GCs." (PMID 38791079, 2024). "In HNSCC, it has been shown that tumor cells, through the secretion of FGF2, promote the activation of the FGF2/FGFR2 axis in cancer-associated fibroblasts (CAFs) in the dermis." (PMID 38248804, 2024). "The patient who underwent LT after second-line FGFR2 inhibitors demonstrated the most profound pathological tumor response, with less than 5% viable tumor tissue in the hepatectomy specimen." (PMID 39544321, 2024). "Our results pointed to the higher FGFR2 expression in luminal tumours and basal-like tumours, and the lowest expression levels in HER2-enriched tumours." (PMID 39596875, 2024). "We identified FGFR2::BICC1 fusions in two tumours, and FGFR2::KCTD1 and TMEM106B::ROS1 as novel fusions with potential therapeutic implications in iCCA and confirmed oncogenic properties of TMEM106B::ROS1 in vitro." (PMID 38877653, 2024). "Of 30 patients tested, 29 had tumor-derived ctDNA detected but only 19 (63%) had confirmation of FGFR2/3 status as documented by local genotyping—12 had fusions and 7 had missense mutations." (PMID 38602417, 2024). "Of note, cases T30 and T35 (carrying p.C382R and p.Y375C mutations, respectively) showed FGFR2 positivity only in the cytoplasm of tumor cells, whereas in the remaining five cases FGFR2 positivity was observed both in the cytoplasm and cell membrane." (PMID 38326380, 2024). "Using the TSVdb database, the expression levels of FGFR2 exon 8 (indicative of FGFR2 IIIb expression) were higher in ER+ than ER− tumours." (PMID 39596875, 2024). "We have calculated both Spearman and Pearson correlation coefficients for NOTCH1 and FGFR2 expression in relation to tumor progression." (PMID 39063983, 2024). "Fibroblast growth factor receptor 2 (FGFR2) is a molecule overexpressed in numerous tumor cells but less on healthy cell surfaces." (PMID 39156005, 2024). "RPLS scores were lower in tumours harbouring IDH1 or IDH2 mutations (all 3 cohorts with data available), as well as FGFR2 fusions (2/3 cohorts)." (PMID 37758326, 2024). "Experimental results indicate that RPT835 inhibits FGF-dependent tumour proliferation and reduces cell migration in FGFR2-expressing TNBC cell lines and PDX models." (PMID 40135140, 2024). "Currently the selection of iCCA patients for FGFR targeted therapies is based on the detection of FGFR2 GAs in the tumor tissue by genetic testing." (PMID 38326380, 2024). "These correlation coefficients indicate a strong positive correlation between NOTCH1 and FGFR2 expression and their relationship with tumor progression, supporting our reported findings." (PMID 39063983, 2024). "To further investigate the relationship between FGFR2 status and the tumor immune microenvironment, we profiled the immune cells that infiltrated into ICC tissues using mIF and IHC assays." (PMID 38986528, 2024). "The high FGFR2 expression in more advanced tumor stages aligns with its role in driving tumorigenesis and supporting the malignant phenotype." (PMID 39063983, 2024).